SMAD4 (SMAD family member 4)
Diseases named in the same sentence as SMAD4 in open-access papers (continued):
Sharing a sentence is not in itself a finding about the gene and the disease.
tumor (continued). "Moreover, the SMAD4 immunohistochemical score at the tumor invasion front in the group treated with chemo-radiation therapy was lower than the score in the upfront surgery group." (PMID 36088360, 2022). "The discrepant observation—tumor suppressor or tumor promotor—may be due to the different roles of SMAD4 during tumor initiation vs. tumor progression." (PMID 35159011, 2022). "To confirm whether the elevated expression of antigen presentation machinery on tumor cells is essential for Smad4KO‐mediated tumor inhibition, we knocked down β2m expression by shRNA in Smad4 KO PDAC cells." (PMID 35064757, 2022). "SMAD4/DPC4 is a tumor suppressor gene that regulates cell growth and a common intracellular mediator that could alter the TGFβ signaling to promote tumor progression." (PMID 36072013, 2022). "For clinical application in the future, our approach might also require biomarkers to identify possible PDAC responders based on tumor-intrinsic SMAD4 status for rational combination regimens with either AKT or TGF-β inhibitors." (PMID 36127339, 2022). "Here, we showed that Smad4 deletion in mouse PDAC tumors resulted in enhanced tumor immunogenicity." (PMID 35064757, 2022). "The great variability observed among the samples could be explained by tumor heterogeneity, but analysis of larger series of samples is still necessary in order to evaluate the biomarker potential of SMAD4–201." (PMID 35034624, 2022). "Evidence indicates that SMAD4 can act as a tumor suppressor gene in gastrointestinal cancer." (PMID 35879950, 2022). "Overexpressed TGF-β drives tumor suppression in SMAD4-positive PDA cells by repressing KLF5." (PMID 35461253, 2022). "These lines of evidence support the hypothesis that the KLF5 protein expression level and SMAD4 status could be possible biomarkers, which are predictive of tumor sensitivity to h4#147D." (PMID 36385956, 2022). "Consistent with the tumor-suppressive function of Smad4, depletion of Smad4 promotes the growth of NMuMG mammary gland epithelial cells; in contrast, the depletion of Smad4 inhibits the metastasis of MDA-MB-231 cells, in agreement with the pro-metastatic role of Smad4." (PMID 35834310, 2022). "According to these data, loss of the SMAD4 gene and upregulation of TGF-β may be associated with a more advanced tumor stage and can promote cancer initiation, progression, and metastasis." (PMID 33672900, 2021). "TGF-β exerts its tumor suppressor properties in a SMAD4 dependent manner." (PMID 34440587, 2021). "The ccRCC and papillary RCC subtypes had higher expression of SMAD4 than chRCC, which may be related to their more invasive tumor behavior." (PMID 34012911, 2021). "Over the past 2 decades, many studies have shown that SMAD4 mutation does not cause tumorigenesis by itself, but it can promote tumor progression caused by other genes." (PMID 34301194, 2021). "Moreover, CRC induction in murine elevated Act-A and inhibited Smad4 proteins, whilst hesperidin treatment decreased the tumour numbers and increased the levels of Act-A and Smad4 in malignant tissues." (PMID 34867090, 2021). "Smad4, a tumor suppressor, is the central intracellular mediator of TGF-β signaling." (PMID 34381046, 2021).
tumor (continued). "SMAD4 plays a critical role in tumor progression and induces proinflammatory cytokines, such as interleukin (IL)-5, IL-6, and IL-13, which might induce a tumor-promoting microenvironment." (PMID 33802174, 2021). "Interestingly, when tumor samples from several of the CONKO-005 trial participants were re-analyzed, a subgroup of patients with a combination of SMAD4 loss and low Mitogen-Activated Protein Kinase 9 (MAPK9) expression benefited from the addition of Erlotinib." (PMID 34778259, 2021). "In addition, the overexpression of ZNF185 has been shown to promote chemoresistance, tumor proliferation, and inhibition of apoptosis by downregulating SMAD4 in PDAC." (PMID 35111149, 2021). "Taken together, these results imply that highly glycolytic tumor cells might impede NK-mediated immunity through SMAD signaling, and such tumor cells might be vulnerable to SMAD4 inhibition." (PMID 33627136, 2021). "Hence, this study measured the genes and proteins of activins, FS and Smad4 in paired normal and cancerous colonic specimens and the results were analysed according to clinical stages, primary tumour sidedness, and Smad4 expression." (PMID 34867090, 2021). "Furthermore, SMAD4 PDA tumor cells-derived EVs overexpressed glycolytic enzymes and subsequently transferred these to myeloid cells, increasing glucose consumption and lactate production, highlighting the Warburg effect in immune cells." (PMID 34207163, 2021). "ROC curve analysis revealed that both PTEN (AUC = 0.992) and SMAD4 (AUC = 0.853) had good discriminative power for differentiating BC from all non-cancer individuals (benign and healthy combined) compared to routine tumor markers CEA (AUC = 0.538) and CA15.3 (AUC = 0.686)." (PMID 33825073, 2021). "In addition, miR-224 directly targets tumor suppressor, TNFAIP1 and SMAD4, to promote tumor growth both in vitro and in vivo in NSCLC." (PMID 33898432, 2021). "Likewise, SMAD4 expression is significantly lower in the tumours within the RAC1Bhigh group (p = 0.0063), suggesting a negative association between SMAD4 mutation and RAC1B expression." (PMID 34564693, 2021). "For example, in patients undergoing pancreaticoduodenectomy, SMAD4 expression predicted improved survival even when adjusted to other prognostic factors including stage, tumor size, surgical margins, lymph node status, and the use of adjuvant chemoradiotherapy." (PMID 34680235, 2021). "Our study showed that ASTX treatment could significantly reverse H. pylori-induced downregulation of Smad4, which functions as a tumor suppressor in gastric epithelial AGS cells." (PMID 34959833, 2021). "It is reported that SMAD4 inhibits epithelial cell proliferation by acting as a tumor suppressor." (PMID 34434896, 2021). "Furthermore, none of the previous studies investigated the expression of activins and FS in relation to primary tumour sidedness and Smad4 status." (PMID 34867090, 2021). "In cytology, the case was negative and in NGS a pathogenic SMAD4 variant was found, indicating high-grade neoplasm/malignancy." (PMID 33536452, 2021). "Moreover, Act-A and FS in malignant tissues linked positively, whereas Act-AB associated negatively, with tumour size, sidedness, histology, tumour grade, numbers of positive lymph nodes, TNM stages, and Smad4 status." (PMID 34867090, 2021).
tumor (continued). "Importantly, mice with the pancreas-specific ablation of either TGFBR2 or SMAD4 show enhanced tumor formation and early mortality." (PMID 34680235, 2021). "The canonical TGF-β/Smad4 signaling pathway acts as a tumor suppressor in early stages, which is characterized by its anti-proliferative activity, ability to induce apoptosis and promote genome stability, while TGF-β acts as a metastasis promoter to stimulate the development of advanced tumors." (PMID 34301194, 2021). "In the past 2 decades, many studies had shown that SMAD4 mutation can not cause tumorigenesis by itself, but it can promote tumor progression caused by other genes." (PMID 34301194, 2021). "SMAD4 is a tumor suppressor gene that regulates gene transcription and cell growth." (PMID 34381313, 2021). "PGM5-AS1 may promote tumor proliferation, migration and invasion by modulating the inhibitory effect of miR-100-5p on the tumor suppressor gene SMAD4." (PMID 34212174, 2021). "Indeed, in different tumor types, inactivation of SMAD4 has been described to promote tumor progression by a number of mechanisms." (PMID 34201758, 2021). "Indeed, as a tumor suppressor gene, SMAD4 is frequently inactivated in cancer by several mechanisms, mostly by genetic alterations but also by promoter methylation." (PMID 34571856, 2021). "Additionally, Charles reported that when SMAD4 was present in tumor cells, TGFβ had induced lethal EMT." (PMID 34048444, 2021). "Preceding publications reported that SMAD4 plays as a tumor inhibitor of ESCC." (PMID 33869216, 2021). "miR-34a is a tumor suppressor and negatively regulates SMAD4." (PMID 33511320, 2021). "The SMAD4 protein expression also differed between tumor sites." (PMID 33509126, 2021). "The model developed here combines clinical variables available preoperatively (tumor morphologic appearance on CT, tumor SUVmax, and clinical stage) and genomic data (SMAD4 and SMARCA4 alterations) that can be obtained from a preoperative biopsy specimen to better guide the therapeutic strategy." (PMID 34290393, 2021). "SMAD4 induced inhibition of TGF-β activity suppresses tumour activity." (PMID 34768988, 2021). "Loss of SMAD4 promotes expression of CCL15 by CRC and recruitment of CCR1+ TANs (CCL15-CCR1 axis) with both arginase-1 (ARG-1) and matrix metalloprotease 9 (MMP-9) activity, forming a premetastatic niche for the disseminated tumor cells —e.g., in the lungs." (PMID 33917620, 2021). "SMAD4 is a widely known tumor suppressor that is inactivated in more than half of PDAC patients." (PMID 34055620, 2021). "PDAC harboring mutant SMAD4 exhibited a high metabolic tumor burden." (PMID 32429474, 2020). "In the backdrop of Apc deletion, removal of the tumor suppressive function of TGFβ/SMAD (through Smad4 deletion) and installation of the tumor promoting function of PI3K/AKT/mTOR (through Pten deletion) independently promotes the formation of SCC of the mouse penis." (PMID 32358507, 2020). "Lastly, ERBB3 and SMAD4 mutated tumors had a significantly higher infiltration of mDCs in the tumor and stromal compartments, and RNF43 mutated tumors had a significantly higher infiltration of iDCs in the tumor compartment." (PMID 33013928, 2020). "Downregulation of sFRP1 and Smad4 could activate Wnt/β-catenin signaling pathway, thereby promoting tumor cell invasion and metastasis." (PMID 33310972, 2020).
tumor (continued). "Loss of SMAD4 inhibits the tumor suppressor effects of TGFβ without affecting tumor response, promoting a more aggressive phenotype." (PMID 32429474, 2020). "Therefore, the relationship between Smad4 and tumor invasion and metastasis has inevitably become a hot topic in recent-year study of tumor invasion and metastasis." (PMID 32897241, 2020). "However, due to the inactivation of the TGF-β signaling mediator, SMAD4, the tumor suppressive role of TGF-β is always impaired in PC." (PMID 33316775, 2020). "Our results suggest that Smad4 could play tumor suppressor roles in both colonic epithelium and NK cells as CRC progresses, thus representing a novel molecular therapeutic target for preventing and/or treating this disease." (PMID 33424832, 2020). "Our current study suggests that the tumor suppressive actions of Smad4 in both colonic epithelium and NK cells could interfere with the transformation of benign to malignant stages of CRC." (PMID 33424832, 2020). "Thus, we propose that B3GNT3 overexpression induces SMAD4 inactivation and promotes tumor growth and metastasis through TGF-β signaling pathway." (PMID 33316775, 2020). "Smad4, is a known tumor suppressor in human CRC in epithelium." (PMID 33424832, 2020). "Based on these data, we conclude that CRC‐associated downregulation of VPS4B does not reflect its own tumor suppressor function but rather represents a passenger alteration co‐existing with concomitant loss of the neighboring 18q‐located tumor suppressors, such as DCC, SMAD2, and SMAD4." (PMID 31930723, 2020). "Loss of SMAD4 expression occurs late in PDAC tumor progression and is correlated with a higher metastatic burden, as well as malignant phenotypes of PDAC, including degree of differentiation, tumor size, and lymph node metastasis." (PMID 32429474, 2020). "This suggests that the anti-tumor effects of NK cells might be impaired in CRC patients because of lower Smad4 levels." (PMID 33424832, 2020). "The TGF-β SMAD4 signalling pathway mediates the tumour-stroma interaction." (PMID 33008426, 2020). "However, in PDAC alterations of TGFβ signaling through the mutation of genes involved in the pathway (e.g., SMAD4, SMAD3, TβR-I, TβR-II, ACVR1B, and ACVR2A), this role is present in 47% of cases, highlighting that TGFβ can sometimes acts as a tumor promoter." (PMID 32429474, 2020). "Correlation between SMAD4 status and tumor stage has been described in other organs." (PMID 30730996, 2019). "In tumor tissues, SMAD4 immunoreactivity varied from weak (middle) to intense (right)." (PMID 31867281, 2019). "Both miR-34a and Smad4 were localized in the cytoplasm and nuclei of the tumor cells." (PMID 31349837, 2019). "These bioinformatics results implicate that SMAD2, SMAD3 and SMAD4 may exert tumor suppressive functions in the prostate, including the inhibition of ETV1’s oncogenic activity." (PMID 31160676, 2019). "Furthermore, loss of tumor suppressive miR-19a-3p leads to activation of SMAD2 and SMAD4, contributing to the formation of bone metastasis in a mouse model." (PMID 31842336, 2019). "High Smad2 and Smad4 nuclear expression with or without cytoplasmic staining in urothelial cancer was associated with low tumor grade (p = 0.003, p = 0.048, respectively)." (PMID 31238579, 2019). "While the kinetic profile of ctgf expression in these contexts is unknown, our observations suggest that higher SMAD4 levels may also allow more sustained ctgf transcription activity in the context of fibrosis and tumor metastasis." (PMID 30926874, 2019). "Indeed, TGFβ is a potent activator of EMP in PDAC cells when its tumour suppressive signals are disrupted through SMAD4 mutations, found in 50% of PDAC tumours." (PMID 31703358, 2019).
tumor (continued). "However, other events distinguish the two tumor types, with primary MOC carrying ERBB2 amplifications and RNF43 mutations, whereas pancreatic tumors show frequent SMAD4 alterations." (PMID 31477716, 2019). "Furthermore, the results suggest that pAMPK probably conducts a tumor-suppressive function through pSMAD2/SMAD4 activation, at least in part." (PMID 31640193, 2019). "Indeed, the tumor-suppressor gene Smad4, whose inactivation is widely accepted as an important genetic hit determining the TGFβ switch, is undisturbed in our cell system." (PMID 31171768, 2019). "The resulting topology integrates centrally involved proteins of the common signaling pathways and generally accepted cancer drivers in CRC—such as APC, p53m, KRAS, DCC, TGFβR, PTEN and SMAD4 allowing a simplified view on the progression from normal cells to tumor cells (Table A2, Figure A8)." (PMID 31861874, 2019). "Additionally, SMAD4 acts as a tumor suppressor and inhibits transforming growth factor-β-mediated signaling." (PMID 31581674, 2019). "Circulating tumor and invasive cells’ SMAD4 expression was measured serially." (PMID 30477242, 2018). "The correlation of immunohistochemical expression with the clinicopathological parameters associated with CRC revealed that high TGF-β expression and low TGF-βR1, TGF-βR2, Smad4, pSmad2/3, and E-cadherin expression were correlated with the tumor–node–metastasis (TNM) stage of the disease." (PMID 30071009, 2018). "Since hetero-oligomerization is needed to bind target-specific transcriptional complexes in the nucleus, two different types of phospho-Smad3 transmit different signals, which is consistent with the ability of Smad4 to act as both a tumor repressor and a tumor activator." (PMID 29874844, 2018). "Decreased TGFβR2 and SMAD4 levels observed in the present study may be responsible for reduced tumor suppressive effects of this pathway in CML." (PMID 29951173, 2018). "Furthermore, we demonstrated that downregulation of miR-301a in BEAS-2B attenuates tumor growth in the xenograft model by targeting SMAD4." (PMID 30185897, 2018). "Our study focused on the role of miR-27a and SMAD4 in HLECs and they may have different functions in tumor cells and endothelial cells." (PMID 29065177, 2017). "We found that SMAD4 mutation was not related to age, race, tumor grade, or presence of distant metastasis." (PMID 28267766, 2017). "CDKN2A (9%), FAT1 (23%), SMAD4 (11%), and CASP8 (13%) mutations were only present in HPV-negative HNSCC cell lines, which was consistent with the HNSCC TCGA data, where each of these mutations occurred in only 1 HPV-positive HNSCC patient tumor." (PMID 29156801, 2017). "They demonstrated association of SMAD4 mutation with mucinous histology but they did not observe any further correlations with age, gender, or tumor stage." (PMID 28267766, 2017). "Given the notion that αvβ6‐targeting should be avoided in tumours that retain canonical signalling, it is noteworthy that αvβ6 inhibition significantly suppressed the invasion of Panc0403 cells that retain wild‐type SMAD4." (PMID 28608476, 2017). "Both WWOX and Smad4 are tumor suppressors and proapoptotic proteins." (PMID 27845895, 2017). "A later analysis of one of the very small tumours of the lower lobe (not of relevance for the clinical handling of the patient) revealed the same KRAS mutation while the SMAD4 mutation was not seen." (PMID 28347348, 2017). "The functions of miR-27a and SMAD4 are likely tumor type- and cell type-dependent." (PMID 29065177, 2017).